FASLG (Fas ligand)
Diseases named in the same sentence as FASLG in open-access papers (continued):
Sharing a sentence is not in itself a finding about the gene and the disease.
Autoimmunity (54 papers, 2005 to 2026). The occurrence of an immune reaction against the organism's own cells or tissues. "FASLG has been reported to be critical in triggering apoptosis of some types of cells such as lymphocytes and defects in this gene may be associated with lymphoproliferation and thus a predisposition to autoimmunity." (PMID 37808112, 2023). "In addition, abnormal neurofibromin production suppresses Fas ligand expression, therefore preventing the apoptosis of CD4+ T cells, which is important for the development of autoimmunity." (PMID 28552839, 2017). "Abnormal production of neurofibromin suppresses expression of fas-ligand, preventing apoptosis of CD4+ T-cells, which may contribute to the development of autoimmunity." (PMID 23691379, 2013).
ovarian carcinoma (52 papers, 2001 to 2025). A malignant neoplasm originating from the surface ovarian epithelium. "Although corticotropin-releasing hormone (CRH) and Fas ligand (FasL) have been documented in ovarian carcinoma, a clear association with tumour progression and immuno-escape has not been established." (PMID 17667919, 2007). "Previous studies of ovarian cancer demonstrated that a high percentage of primary tumors in HGSOC are Fas ligand positive." (PMID 36077825, 2022). "Characterization of MV derived from sera of head and neck squamous cell carcinoma (HNSCC) patients and ascites from ovarian carcinoma patients demonstrates increased expression of IL-10, TGFβ, and Fas ligand (FasL)." (PMID 31681327, 2019). "We have previously reported the presence of functional DcR3 in advanced Epithelial Ovarian Cancer (EOC) ovarian cancer demonstrating that naturally occurring DcR3 inhibited Fas-ligand mediated apoptosis." (PMID 22583667, 2012). "EVs derived from prostate and ovarian cancer express Fas ligand (FasL, also known as CD95L) and tumor necrosis factor-related apoptosis-inducing ligand (TRAIL) (which induces T cell apoptosis), respectively; thus, they act as antigen-presenting death signals for CD8+ T cells." (PMID 40182121, 2025). "Additionally, soluble Fas ligand has been previously reported to be in vesicles in the ascites of ovarian cancer patients, although it is unclear if these were chemo-naïve samples or ascites collected following treatment." (PMID 36077825, 2022). "In addition to reprogramming the immune cell gene profile, ovarian cancer cells release Fas ligand (FasL)-carrying exosomes which downregulate the expression of the surface T cell receptors/CD3-zeta (ζ) and promote T cell apoptosis." (PMID 33228245, 2020). "In certain cancer types, different eQTL-lncRNAs pairs influence the same set of mRNA targets; for example, in ovarian cancer, two eQTL (2p25.2 and 7q34) eventually regulate the same set of mRNAs (FASLG, GZMM, PYHIN1 and TRAT1) but through different elncRNAs (AC092580.4 and TRBV11-2)." (PMID 33194770, 2020). "In addition to reprogramming the immune cell gene profile, ovarian cancer cells release Fas ligand (FasL)-carrying exosomes which downregulate the expression of the surface T-cell receptor/CD3- zeta (ζ) and promote T-cell apoptosis." (PMID 31409361, 2019). "IL-24 treatment is known to induce the expression of various members of the extrinsic apoptotic pathway, such as Fas cell surface receptor (Fas), Fas ligand (FasL), Fas-associated death domain (FADD) in human ovarian cancer cells, and death receptor 4 (DR4), in colorectal cancer cell lines." (PMID 30424508, 2018). "Activation of JNK/p38 MAPK pathways in response to cisplatin could lead to Fas ligand induction and cell death in ovarian carcinoma cells." (PMID 22216282, 2011). "In addition, CRF induces local immunosuppression by promoting apoptosis of cytotoxic T-cell via the prduction of Fas ligand (FasL) in ovarian cancer cells." (PMID 20875132, 2010).
glioblastoma (49 papers, 2003 to 2025). The most malignant astrocytic tumor (WHO grade IV). "For example, DcR3, which binds Fas ligand by a competitive mechanism and blocks Fas ligand-mediated apoptosis, was identified to be upregulated in glioblastoma and carcinomas of lung and colon." (PMID 33916780, 2021). "Previous investigations of miR-21 have mostly been focused on its role in cancer; for example, it has been shown that miR-21 can affect the apoptosis and proliferation of glioblastoma cancer stem cells by targeting fas antigen ligand (FASLG)." (PMID 30459705, 2018). "TRD mediated antitumor effects were postulated as in part being based on an increase in Fas-ligand induced apoptosis in glioblastoma." (PMID 25568670, 2014). "A recent study provided evidence that CD95 (the receptor of CD95L, Fas Ligand) is overexpressed in glioblastomas compared to normal neural cells and its level of expression was associated to negative prognosis and to epithelial to mesenchymal transition (EMT) and CSC gene signatures." (PMID 30279357, 2018). "In contrast, siRNA down regulation of gelatinase B/MMP-9 expression induces apoptosis in human glioblastoma cells in association with Fas death receptor-mediated caspase 3 and caspase 8 cleavage, implicating gelatinase B/MMP-9 in protecting glioblastoma cells against Fas ligand-mediated apoptosis." (PMID 24473089, 2014). "Similarly, glioblastoma favors the expression of several inhibitory molecules such as signal transducer and activator of transcription 3 (STAT3) and Fas ligand (FasL) which aggravate immune inhibitory signals and promote T-cell apoptosis, respectively." (PMID 33202642, 2020).
lung carcinoma (49 papers, 2005 to 2025). "Studies have demonstrated that TDP-43 interacts with Fas ligand mRNA in lung cancer, enhancing the stability of the Fas ligand mRNA, promoting apoptosis, and ultimately impeding lung cancer growth." (PMID 38281298, 2024). "To find out how noncancerous cells react to the treatment with ActD + Nut3a + FASLG, we compared how normal human fibroblasts (GM07492) and lung cancer cells (A549) grow after pre-treatment with ActD + Nut3a with subsequent exposure to FASLG." (PMID 39068622, 2024). "The CD44-HA interaction has been found to promote immune evasion by inhibiting Fas expression during Fas/Fas ligand T cell-mediated cytotoxicity in lung cancer cells." (PMID 39333557, 2024). "Immune-related plasma proteins in lung cancer patients were quantified, and Fas ligand (FASLG) and inducible T-cell co-stimulator ligand (ICOSLG) were demonstrated to be associated with response and survival." (PMID 38067332, 2023). "In vitro, an RLR agonist Poly(I:C)-HMW (High Molecular Weight)/LyoVecTM [Poly(I:C)-HMW] sensitised in vitro human lung cancer cells to Fas ligand (FasL)-induced apoptosis by radiotherapy." (PMID 36106115, 2022). "The fact that many LCs possess this decoy receptor suggests that Fas/Fas ligand must play an important role in lung cancer defense." (PMID 22899945, 2012). "In addition, FOXO3a negatively regulates the expression of miR-21, which targets the 3’UTR of the Fas ligand (FasL), a pro-apoptotic factor, and enhances doxorubicin-induced apoptosis in lung cancer cells." (PMID 39930542, 2025). "To find out if we could break this resistance, we pre-exposed A549 lung cancer cells to ActD and Nut3a for 48 h and then treated them for 2.5 h with FASLG at 100 or 200 ng/ml concentrations." (PMID 39068622, 2024). "CTLs can express Fas ligand (CD95L) and kill cells that are Fas+, which can include lung cancers." (PMID 22899945, 2012). "But Fas ligand also recruits neutrophils into the lung cancers via the production of PGE2." (PMID 22899945, 2012). "We accessed data from lung cancer biopsies and healthy lung tissue and were able to validate MIC-A and FASLG." (PMID 36359256, 2022). "Although the function of this lncRNA has not been assessed in lung cancer cells yet, a previous study has shown the co-expression of Fas and Fas ligand (FasL) in lung cancer cell lines and the apoptotic effect of agonistic anti-Fas antibody in these cells." (PMID 30866866, 2019).
leukemia (45 papers, 2002 to 2025). A malignant (clonal) hematologic disorder, involving hematopoietic stem cells and characterized by the presence of primitive or atypical myeloid or lymphoid cells in the bone marrow and the blood. "Conversely, blocking miR-149-5p results in increased FASLG expression, which in turn promotes apoptosis in leukemia cells." (PMID 40971385, 2025). "It is reported that cladribine induces human leukemia cell line apoptosis through the Fas/Fas ligand pathway 36, our results further established the role of cladribine in inducing extrinsic apoptotic pathway." (PMID 32624694, 2020). "Different leukemia cell lines exposed to arsenic trioxide showed increased gene or protein expression of FASLG." (PMID 33381488, 2020). "Elevated serum concentrations of soluble FASLG have been detected in patients with leukemia, lymphoma and multiple solid tumors." (PMID 33381488, 2020). "Consistent with this view, both TNFα and Fas ligand have been shown to induce rRNA degradation in human leukemia cells." (PMID 26911141, 2016). "The Fas (CD95)/Fas ligand (CD178) system has a potential role in cytotoxic killing of some leukemias." (PMID 22084681, 2010). "Effector cytotoxic T cells as well as T-LGL leukemia cells express Fas ligand, a member of the tumor necrosis factor family, which can bind Fas and initiate apoptosis in the target cells through this pathway." (PMID 18474096, 2008). "More recently, TNFα-superfamily death receptor named Fas (CD95) has become the focus of attention due to the critical role of Fas ligand (FasL) on the surface of CAR-T cells in instigating bystander killing of antigen−/FasR+ cancer cells in leukemia clinical trials." (PMID 40593750, 2025). "Similarly, exosomes carry Fas ligand (FAS-L), NPM1, FLT3, matrix metallopeptidase 9 (MMP9), insulin-like growth factor type 1 receptor (IGF1-R), CXCR4, and chaperones to alter the BM microenvironment and to improve the survival of leukemia cells, especially LSCs." (PMID 35865470, 2022).
gastric cancer (44 papers, 2005 to 2025). A primary or metastatic malignant neoplasm involving the stomach. "MiR-21 and its targets FASLG and B-cell translocation gene 2 (BTG2) are implicated in the malignant progression of MNNG-induced gastric cancer." (PMID 38460046, 2024). "Studies have revealed that increased FASLG expression facilitate development and progression of tumors, including gastric cancer." (PMID 29364829, 2018). "Comparisons of serum levels of insulin-like growth factor I, II, and binding protein 3, transforming growth factor β-1, soluble fas ligand and superoxide dismutase activity in stomach cancer cases and their controls." (PMID 16127223, 2005). "Prunin treatment could potentially increase the expression of death receptors Fas Ligand (FasL) protein in human gastric cancer cells." (PMID 40141319, 2025). "We found that the methylation of FASLG was studied in Acute Coronary Syndrome and gastric cancer." (PMID 35174173, 2021). "In gastric cancer cells (BGC-823), celecoxib inhibits the expression of two anti-apoptotic proteins, Bcl-2 and Fas ligand (FasL), and increases the expression of the apoptotic Fas protein." (PMID 36672424, 2023). "However, extrinsic apoptosis proteins [Cle-Caspase 8, DR4, Fas, Fas ligand (FasL)] were not significantly altered, suggesting that Cos induced apoptosis via intrinsic (mitochondrial) pathway in gastric cancer cells." (PMID 34869312, 2021).
prostate carcinoma (43 papers, 1999 to 2025). A carcinoma that arises from epithelial cells of the prostate gland. "It was reported that apoptotic cell death of PTEN-deficient prostate cancer cells induced by LY294002 or expression of wild type PTEN can be abrogated by disrupting Fas/Fas ligand (FasL) interactions." (PMID 19384426, 2007). "A previous study revealed that TDEs from prostate cancer carry Fas ligand (FasL), inducing the apoptosis of CD8+ T cells." (PMID 38562940, 2024). "Bax-based gene therapy techniques have demonstrated potential in eliciting bystander death effects in prostate cancer cells in conjunction with other apoptotic molecules such as Fas Ligand and TRAIL." (PMID 39554609, 2024). "Nitric oxide has been shown to inhibit YY1 binding to the Fas promoter resulting in Fas upregulation and cell sensitization to Fas ligand–induced apoptosis in prostate cancer." (PMID 34597666, 2021). "In prostate cancer, TDEs expressing Fas ligand (FasL) decreased T cell proliferation and induced T cell apoptosis in a dose-dependent manner." (PMID 33530529, 2021). "It is likely that one or more of these proteins are differentially regulated in prostate cancer and as a result increase the threshold required for Fas receptor activation and apoptosis following engagement of Fas receptor with Fas ligand." (PMID 14612908, 2003). "In addition to its serotype affecting the development of prostate cancer, adenovirus expressing Fas ligand (FasL) can induce apoptosis in a group of prostate cancer cell lines." (PMID 34956913, 2021). "Thus, it has been shown that Fas ligand (FasL) is secreted by prostatic carcinoma cells and together with Fas/CD95 plays a key role in the development of abnormal cells." (PMID 33737530, 2021). "Activation of FOXOs (such as FoxO1 in prostate cancer cells) triggers cell cycle arrest and induces cell apoptosis via increasing the levels of Fas‐L (Fas ligand), TRAIL (tumor necrosis factor‐related apoptosis‐inducing ligand), and Bim in various types of cells." (PMID 29533017, 2018). "Silencing Siah2 or POSH in prostate cancer cells led to increased caspase activity and apoptosis in response to both TRAIL and Fas ligand." (PMID 21586138, 2011). "Despite expressing both Fas and Fas ligand, DU145 and LNCaP prostate cancer cells were resistant to anti-Fas-induced cell death." (PMID 10408840, 1999). "On the molecular level, SFN induces oxidative stress in cells, increases the level of Fas ligand (FasL), activates caspase 8 and cleavage of BH3-interacting domain death agonist (Bid), and in consequence triggers apoptosis in androgen-independent prostate cancer cells (PC-3 and DU-145)." (PMID 34830408, 2021).
hepatocellular carcinoma (41 papers, 2000 to 2026). A malignant tumor that arises from hepatocytes. "This approach identified a highly activated, tissue-resident CD8+ T cell population that caused Fas ligand–dependent (FasL-dependent) apoptosis in hepatoma cells, consistent with their role in liver damage, and expressed IFN-γ, which can drive the inflammatory infiltrate." (PMID 36594467, 2023). "Early growth response 3 (EGR3), as a novel zinc finger transcription factor, is a newly discovered tumor suppressor gene, which can inhibit the growth of hepatocellular carcinoma, gastric cancer, and other cancer cells by up-regulation of Fas ligand." (PMID 32075046, 2020). "We are focused on irradiation facilitating Fas ligand secretion in hepatoma cells and increasing both hepatocytes and cancer cells injury." (PMID 29098144, 2017). "The status of Fas and Fas ligand (FasL) expression can also predict hepatocellular carcinoma recurrence." (PMID 21655114, 2011). "The status of Fas and Fas ligand (Fas L) expression was investigated in this study for 103 hepatocellular carcinomas (HCC)." (PMID 10735508, 2000). "Moreover, RSV protects the liver against hepatocellular carcinoma and induces cancer cell death in cultured cells of hepatocytes in hepatocellular carcinoma by regulating Fas and Fas-ligand." (PMID 38675230, 2024). "A distinct mechanism was also reported in hepatocellular carcinoma, where EGR3 promoted Fas ligand expression to drive apoptosis." (PMID 40649712, 2025). "Particularly, Tregs expressing Fas ligand (FasL) has been shown to selectively induce apoptosis in CD8+ T cells within tumor microenvironments, including head and neck squamous cell carcinoma (HNSCC) and hepatocellular carcinoma (HCC)." (PMID 41596443, 2026). "Interestingly, dexamethasone does not protect rat hepatoma cells from apoptosis induced by the extrinsic pathway trigger Fas Ligand (FasL)." (PMID 24709697, 2013).
lymphoma (39 papers, 2007 to 2025). A malignant (clonal) proliferation of B- lymphocytes or T- lymphocytes which involves the lymph nodes, bone marrow and/or extranodal sites. "The reduced FAS levels induced by ARID1A loss rendered lymphoma cells resistant to both soluble and T cell membrane-anchored FASLG-induced apoptosis, and significantly diminished CAR T cell killing in functional experiments." (PMID 39843653, 2025). "As such, mutations of PRF1 (encoding for perforin) are frequently found in patients with anaplastic large cell lymphoma (ALCL) and ALL, and mutation of FASLG (encoding for FasL) was observed in lymphoma patients." (PMID 35720306, 2022). "Specifically, amplification of the FAS ligand (FASL) (q = 0.027) located at the locus 1q24.3 might enable lymphoma cells to induce apoptosis of surrounding lymphocytes." (PMID 36604606, 2023). "Likewise, a significant proportion of patients with lymphoma harbors mutations that inactivates perforin and Fas ligand (FASLG) genes, which are associated with absent NK cell activity." (PMID 31569769, 2019).
Stroke (37 papers, 2011 to 2025). Sudden impairment of blood flow to a part of the brain due to occlusion or rupture of an artery to the brain. "Post-stroke, neurons release soluble Fas ligand (sFasL), which activates the phosphorylation cascade of the JAK2/STAT3/NF-κB pathway." (PMID 38887610, 2024). "Animal studies have shown that the expression of TNF, TNF-related inducing ligand (TRAIL), and Fas ligand (FasL) are all upregulated after ischemia, and these molecules worsen stroke prognosis to some extent." (PMID 35356292, 2022). "Neuronal miR-21 appears to act as a pro-survival factor: overexpressing miR-21 in cultured neurons subjected to oxygen-glucose deprivation (an in vitro stroke model) significantly inhibited apoptosis, in part by directly suppressing the pro-apoptotic Fas ligand (FASLG)." (PMID 40981170, 2025). "Importantly, a significant reduction in the volume of the infarcted area occurred in hybrid mice expressing nonfunctional Fas ligand and in TNF knockout mice 24 h after stroke." (PMID 36824441, 2022).